ENSG00000285655 (novel protein)
Gene: Protein-coding gene on chromosome 8 (66,430,185 to 66,445,324, forward strand). Ensembl gene ENSG00000285655.
Genetic constraint (gnomAD): Loss-of-function variants: 6 observed, 7.79 expected, observed/expected ratio (o/e) 0.77, 90% interval 0.42 to 1.5. That is too few expected variants to judge how well the gene tolerates losing a copy. Missense variants: 105 observed, 112.85 expected, observed/expected ratio (o/e) 0.93, 90% interval 0.79 to 1.09. Synonymous variants: 33 observed, 41.13 expected, observed/expected ratio (o/e) 0.8, 90% interval 0.61 to 1.07.